IL17B (interleukin 17B)
Description:
Stimulates the release of tumor necrosis factor alpha and IL-1-beta from the monocytic cell line THP-1.
Synonyms: IL-17B; IL-20; NIRF; ZCYTO7; MGC138900; MGC138901
Tractability: Antibody: UniProt places it where antibodies can reach, with medium confidence; UniProt predicts a signal peptide or a membrane-spanning region; its Gene Ontology location is reachable by antibodies, with medium confidence.
Gene: Protein-coding gene on chromosome 5 (149,371,324 to 149,404,202, reverse strand). Ensembl gene ENSG00000127743.
Subcellular location: Secreted
Gene Ontology:
Molecular function: cytokine activity
Biological process: cell-cell signaling; immune response; interleukin-17-mediated signaling pathway; positive regulation of interleukin-13 production; positive regulation of interleukin-5 production; protein K63-linked ubiquitination; regulation of cell growth; T-helper 17 type immune response; inflammatory response
Cellular component: plasma membrane; extracellular region
Genetic constraint (gnomAD): Loss-of-function variants: 14 observed, 14.59 expected, observed/expected ratio (o/e) 0.96, 90% interval 0.63 to 1.5. The upper end of that interval is the gene's LOEUF score, 1.5, which puts it in group 6 of 6, group 1 being the genes least tolerant of losing a copy. Missense variants: 233 observed, 258.4 expected, observed/expected ratio (o/e) 0.9, 90% interval 0.81 to 1. Synonymous variants: 105 observed, 98 expected, observed/expected ratio (o/e) 1.07, 90% interval 0.91 to 1.26.
Homologues: Orthologues: chimpanzee IL17B (99% identical), macaque IL17B (97% identical), dog IL17B (92% identical), guinea pig IL17B (91% identical), pig IL17B (89% identical), mouse Il17b (88% identical), rat Il17b (88% identical), rabbit IL17B (88% identical). Paralogues in human: IL17C (24% identical), IL17D (24% identical), IL17F (23% identical), IL17A (22% identical), IL25 (17% identical).
Diseases named in the same sentence as IL17B in open-access papers:
IL17B is named in the same sentence as 61 diseases in open-access papers, as found by Europe PMC text mining. Sharing a sentence is not in itself a finding about the gene and the disease. The quoted sentences say what the papers report.
breast carcinoma (28 papers, 2014 to 2024). "Meanwhile, the high expression of the IL-17B/IL-17RB axis has been associated with poor prognosis of several cancers, including breast cancer, lung cancer, and gastric cancer." (PMID 37686343, 2023). "High expression of IL‐17B and IL‐17RB has been associated with poor prognosis in different cancer types, including breast cancer, glioblastoma, lung cancer, gastric cancer, and colon cancer." (PMID 36325957, 2023). "High levels of IL-17B have also been associated with poor prognosis in patients with pancreatic, lung or breast cancer, suggesting that the same signaling is exploited by cancer cells for survival, proliferation, and migration." (PMID 33244315, 2020). "Here we found that high expression of IL-17B and IL-17RB is associated with poor prognosis in patients with breast cancer and that IL-17B expression upregulation is specifically associated with poorer survival in patients with basal-like breast cancer." (PMID 29371916, 2017). "Moreover, a study revealed that IL-17B levels are highly expressed and associated with the prognosis of pancreatic, lung, and breast cancers." (PMID 37686343, 2023). "Moreover, recent work has demonstrated that elevated IL-17B is associated with poor prognosis in the patients with pancreatic, gastric, lung, and breast cancers." (PMID 36267311, 2022). "Moreover, the finding that elevated IL-17B is associated with poor prognosis in patients with pancreatic, gastric, lung, and breast cancer strengthens the results obtained in pre-clinical studies and highlights its clinical relevance." (PMID 32373132, 2020). "IL-17B and its receptor have been identified to be related to the progression and development of breast cancer." (PMID 37212877, 2023). "IL-17B in breast cancer cells activated ERK and NF-kB pathways and enhanced the expression of anti-apoptotic Bcl-2 family members." (PMID 35392087, 2022). "Combination of 6 protein markers (Adipsin, Leptin, Syndecan-1, Basic fibroblast growth factor, Interleukin 17B and Dickopff-3) resulted in 65% sensitivity and 80% specificity in detecting breast cancer." (PMID 34997107, 2022). "In breast cancer, high expression of IL17RB is associated with poor prognosis that is mainly the result of the interaction between IL-17B and IL17RB." (PMID 36267311, 2022). "Amplified signaling of IL17RB and related ligand IL17B enhanced tumorigenicity in breast cancer cells and activated NF-κB to upregulate anti-apoptotic factor Bcl-2 and induced etoposide resistance." (PMID 34724890, 2021). "The expression levels of IL-17B and IL-17D in breast cancer were quantitatively analyzed because they showed much higher expression than other cytokines from the IL-17 family." (PMID 33102239, 2020). "Engagement of IL-17B with its receptor induces Nf-kB-mediated upregulation of Bcl-2 expression, and resistance of mammary cancer cells to etoposide." (PMID 33244315, 2020). "By contrast, IL-17B is reported to be closely related to certain diseases, particularly tumors such as breast cancer, gastric cancer, and pancreatic cancer." (PMID 30345318, 2018). "To further refine the prognostic value of IL-17B per se, we next analyzed the microarray results of a cohort of 1809 patients with breast cancer." (PMID 29371916, 2017). "Altogether these results emphasize the specific effect of IL-17B on resistance of breast cancer cell lines to paclitaxel-based chemotherapy." (PMID 29371916, 2017). "We thus evaluated the expression of IL-17B and IL-17RB by real-time quantitative PCR in biopsies from a cohort of patients with breast cancer (n = 143) and 10 years of follow-up." (PMID 29371916, 2017). "We next focused on the signaling pathways activated in human breast cancer cell lines upon incubation with IL-17B." (PMID 29371916, 2017).
breast carcinoma (continued). "Altogether our results emphasize the role of the IL-17B/IL-17RB signaling pathway in breast tumors and identify IL-17B and its receptor as attractive therapeutic targets for potentiating breast cancer chemotherapy." (PMID 29371916, 2017). "We thus focused on IL-17B role in breast cancer by using luminal and triple negative (TN)/basal-like tumor cell lines." (PMID 29371916, 2017). "Specifically, IL-17B produced by breast cancer cells promotes anti-apoptotic signaling and tumor survival through activation of the NF-κB pathway." (PMID 29371916, 2017). "The observation that IL-17B effects were not limited to basal-like breast cancer cell lines suggests that the IL-17B/IL-17RB role in TN/basal-like breast tumors is mainly due to upregulation of this pathway rather than to TN/basal-like-specific mechanisms." (PMID 29371916, 2017). "Consistently with this idea, previous studies have shown that the IL-17RB/IL-17B signaling pathway promotes tumorigenicity and etoposide resistance in breast cancer cells through NFκB activation and Bcl-2 up-regulation." (PMID 27462789, 2016). "Wen-Hwa and co-workers first reported that amplified IL-17B/IL-17RB signaling promotes breast cancer tumorigenicity by activating nuclear factor-kB, to upregulate the antiapoptotic factor Bcl-214." (PMID 27146881, 2016). "It was reported that IL-17A and IL-17B neutralizing antibody treatments led to decreased breast cancer growth in mice." (PMID 26154409, 2015). "Therefore, IL-17B can promote the growth of breast cancer tumor complexes in mice, while IL-17E can inhibit this process." (PMID 36267311, 2022). "At the same time, more and more evidences have proved that IL-17B/IL-17RB get trapped in the occurrence and poor prognosis of patients with malignant tumors such as pancreatic cancer, gastric cancer, lung cancer and breast cancer." (PMID 35392087, 2022). "Moreover, IL-17RB and IL-17B amplification can promote tumorigenicity in breast cancer via the activation of NF-kB and Bcl-2." (PMID 35954312, 2022). "Mechanistic studies in the MDA-MB 361, MDA-MB468, and MCF-7 breast cancer cell lines revealed that IL-17B promotes breast cancer cells survival in vitro by activating the ERK and NF-kB pathways and by enhancing the expression of anti-apoptotic Bcl-2 family members." (PMID 32373132, 2020). "Similarly, IL-17B or IL-17RB silencing in cancer cells or treatment with antibodies targeting IL-17RB reduced proliferation of MDA-MB361 breast cancer cells and MOLM-13 AML cells in vitro and tumor growth in vivo in xenograft models based on these cell lines." (PMID 32373132, 2020). "Because IL-17B and IL-17E share the same receptor heterodimer, and IL-17E induces apoptosis in mammary cancer cells, an opposing role for IL-17B and IL-17E can be hypothesized in breast cancer." (PMID 33244315, 2020). "Finally, our results emphasize the role of the IL-17B/IL-17RB signaling pathway in breast cancer and identify IL-17B and its receptor as attractive therapeutic targets for therapy." (PMID 29371916, 2017). "Although high IL-17RB expression was previously associated with poor prognosis in patients with breast cancer, the prognostic value of IL-17B per se has never been investigated." (PMID 29371916, 2017). "Importantly when we examined IL-17B expression on a human tissue array of breast cancer and metastasis, we found that IL-17B is mainly expressed by the tumor cells." (PMID 29371916, 2017). "Although these data must be confirmed in a larger cohort of patients, they indicate that in addition to IL-17RB, IL-17B expression level also could influence breast cancer prognosis." (PMID 29371916, 2017). "Thus, various human breast cancer cell lines, in which IL-17RB expression was confirmed by flow cytometry, were cultured in the presence of 10 ng/mL of recombinant human IL-17B (rIL-17B) for 72 h and then incubated with paclitaxel at different concentrations." (PMID 29371916, 2017).
breast carcinoma (continued). "Furthermore, since IL‐17B/IL‐17RB signaling activates NF‐κB in human breast cancer, NF‐κB nuclear translocation can serve as the measurement for the consequence of Il‐17rb induction." (PMID 28993429, 2017). "As we previously reported for IL-17A, IL-17B present in the tumor microenvironment could be an important cancer cell survival factor and a mediator of therapy resistance in breast cancer." (PMID 29371916, 2017). "Indeed, unlike IL-17B, IL-17E (or IL-25) causes caspase-mediated apoptosis of breast cancer cells and reduces colony formation of IL17RB-expressing breast tumor cell lines in vitro." (PMID 32373132, 2020). "However, the molecular mechanisms governing IL-17B expression upregulation in breast cancer cells or in their microenvironment are unknown and they deserve additional investigations." (PMID 29371916, 2017). "Recent studies showed that the IL17B/IL17RB cascade promotes antiapoptosis and tumorigenesis in breast cancer and facilitates invasion, vasculogenic endothelial cells and the macrophage recruitment of pancreatic cancer cells." (PMID 39590310, 2024). "In breast cancer cell lines BT20, MDA-MB-468, and MCF-7, IL-17B induced resistance to paclitaxel, and activation of the extracellular signal-regulated kinase 1/2 (ERK1/2) pathway, leading to the upregulation of B-cell lymphoma 2 (Bcl-2)." (PMID 35954312, 2022). "Recently, another study shows that high expression of IL17B and its receptor IL17RB relates to poor prognosis of breast cancer patients." (PMID 35373393, 2022). "Eight markers (FGF2, IL17B, IP10, MIG, MIP1d, LOX1, OPN and SDC1) found to be upregulated in primary tumours were present in higher concentration in plasma of breast cancer patients." (PMID 34997107, 2022). "Based on the results, it seemed that IL17B, NFKBIE and SERPINA3 mainly prompted the development of breast cancer." (PMID 33785008, 2021). "ShRNA-dependent reduction of IL-17B decreases tumor growth and invasiveness of MDA-MB468 human breast cancer cells." (PMID 32373132, 2020). "Then, we analyzed microarray data of 1809 patients with breast cancer, and found that high IL-17B expression was significantly correlated with poorer prognosis in the whole population and in the basal-like subtype, but not in other breast cancer subtypes." (PMID 32373132, 2020). "Reinforcing such observation, qRT-PCR analysis of TILs expanded from 4 breast cancer patients’ biopsies showed that all the 4 samples were negative or limit to detection (TIL AL) for IL-17B mRNA expression, while half of them expressed IL-17A mRNA." (PMID 29371916, 2017). "Moreover, the signaling pathway of interleukin-17B (IL-17B)/IL-17B receptor may mediate the interaction between human MSC and breast cancer cells." (PMID 26305552, 2015).
pancreatic cancer (13 papers, 2016 to 2025). "It was also found that overexpression of IL-17RB was associated with metastasis and poor clinical outcome of pancreatic cancer, and impairing IL-17B-IL-17RB signaling blocked metastasis of pancreatic cancer." (PMID 36569325, 2022). "In solid tumors, amplified IL-17B/IL-17RB signaling is critical for breast and pancreatic tumorigenesis and elevated IL-17RB expression has been associated with the shortest survival rates in patients with breast or pancreatic cancer." (PMID 29371916, 2017). "IL-17B enhanced the invasion and metastasis ability of pancreatic cancer cells by activating IL-17RB and its downstream ERK1/2 signaling pathway." (PMID 41384105, 2025). "IL-17B is widely expressed in the stomach, pancreas, intestine, and other tissues, and it affects the pathogenesis of malignant tumors such as gastric and pancreatic cancer." (PMID 37686343, 2023). "Activating IL-17B/RB pathway in pancreatic stellate cells promotes pancreatic cancer metabolism and growth." (PMID 37686343, 2023). "They subsequently confirmed that the metastatic ability of pancreatic cancer cells was significantly inhibited by blocking IL-17B/IL-17RB signaling with monoclonal antibodies that targeted IL-17RB." (PMID 33649532, 2021). "The IL-17B concentration in the tumor tissue was significantly higher at the protein level, showing that IL-17B is present in pancreatic cancer." (PMID 34771503, 2021). "Exosomes from pancreatic cancer patients contained more IL-17B compared with healthy controls, suggesting that IL-17B-carrying EVs upregulate IL-17RB expression in PSCs." (PMID 34771503, 2021). "It remains an open question if and how IL-17B mediates tumor-to-stroma signaling in pancreatic cancer." (PMID 34771503, 2021). "Here we ask if PSCs interact with pancreatic cancer cells through Interleukin 17B/Interleukin 17B receptor (IL-17B/IL-17RB) cell-cell signaling." (PMID 34771503, 2021). "The inhibition of IL-17B using shRNA or treatment with IL-17B blocking antibody reduced pancreatic tumor growth and prevented metastasis formation in a mouse xenograft model." (PMID 34771503, 2021). "Taken together, these results suggest that IL17B/IL-17RB signaling not only emerges as an important regulator of pancreatic cancer growth and metastasis, but is a feasible target for pancreatic cancer treatment." (PMID 33082357, 2020). "In pancreatic cancer cell lines, IL-17B activates the ERK1/2 pathway and induces the production of the chemokines CCL20, CXCL1, IL-8 and TFF1." (PMID 29371916, 2017). "IL-17A and IL-17B were two subtypes closely related to pancreatic cancer in the IL-17 family." (PMID 41384105, 2025). "We hypothesized that pancreatic cancer cells stimulate the upregulation of IL-17RB expression in PSCs through IL-17B." (PMID 34771503, 2021). "Blocking IL-17B/RB to inhibit the tumor to stroma crosstalk could be a potential targeted therapy for pancreatic cancer." (PMID 34771503, 2021). "IL-17A and IL-17B are primarily involved in the regulation of the tumor immune microenvironment, and they particularly play a special role in the drug resistance and inflammatory response in pancreatic cancer, according to our overview of six different cytokines." (PMID 37686343, 2023). "Conversely, IL-17RB or IL-17B knockdown in CFPAC-1 and BxPC3 pancreatic cancer cell reduces their soft agar colony formation in soft agar and cell invasion in vitro." (PMID 32373132, 2020). "Together, these results indicate IL17B/IL-17RB signaling is potentially involved in transcriptional regulation of MUC1 and MUC4 expression in pancreatic cancer cells." (PMID 33082357, 2020). "Thus, besides IL-17A, IL-17B also could play an important role in tumor progression through its binding to IL-17RB and might represent a potential therapeutic target in solid tumors, such as breast and pancreatic cancers." (PMID 29371916, 2017).
pancreatic cancer (continued). "The IL-17B/RB pathway has been shown to enhance the expression of chemokines CCL20, CXCL1, IL-8, and TFF1 by regulating the ERK1/2 pathway, thereby promoting metastasis and malignancy in pancreatic cancer." (PMID 37686343, 2023). "The metabolic role of interleukin 17B/interleukin 17B receptor (IL-17B/RB) has not been adequately studied in pancreatic cancer and is poorly understood." (PMID 34771503, 2021).